RPL39L (ribosomal protein L39 like)
Description:
Male germ cell-specific component of the ribosome, which is required for the formation of sperm and male fertility. Replaces the RPL39 paralog in the ribosome of male germ cells. The ribosome is a large ribonucleoprotein complex responsible for the synthesis of proteins in the cell. The male germ cell-specific ribosome displays a ribosomal polypeptide exit tunnel of distinct size and charge states compared with the classical ribosome. It is responsible for regulating the biosynthesis and folding of a subset of male germ-cell-specific proteins that are essential for the formation of sperm.
Synonyms: RPL39L1; L39-2
Tractability: PROTAC: ubiquitination databases record sites on it.
Gene: Protein-coding gene on chromosome 3 (187,120,927 to 187,180,972, reverse strand). Ensembl gene ENSG00000163923.
Subcellular location: Cytoplasm
Pathways (Reactome):
Metabolism of proteins: Eukaryotic Translation Termination; Formation of a pool of free 40S subunits; GTP hydrolysis and joining of the 60S ribosomal subunit; L13a-mediated translational silencing of Ceruloplasmin expression; PELO:HBS1L and ABCE1 dissociate a ribosome on a non-stop mRNA; Peptide chain elongation; Ribosome Quality Control (RQC) complex extracts and degrades nascent peptide; SRP-dependent cotranslational protein targeting to membrane; ZNF598 and the Ribosome-associated Quality Trigger (RQT) complex dissociate a ribosome stalled on a no-go mRNA
Metabolism of RNA: Major pathway of rRNA processing in the nucleolus and cytosol; Nonsense Mediated Decay (NMD) enhanced by the Exon Junction Complex (EJC); Nonsense Mediated Decay (NMD) independent of the Exon Junction Complex (EJC)
Cellular responses to stimuli: Response of EIF2AK4 (GCN2) to amino acid deficiency
Developmental Biology: Regulation of expression of SLITs and ROBOs
Disease: Viral mRNA Translation
Metabolism: Selenocysteine synthesis
Gene Ontology:
Molecular function: protein binding; structural constituent of ribosome
Biological process: spermatogenesis; cytoplasmic translation; translation
Cellular component: cytosolic large ribosomal subunit; cytoplasm; ribosome
Genetic constraint (gnomAD): Loss-of-function variants: 3 observed, 5.24 expected, observed/expected ratio (o/e) 0.57, 90% interval 0.26 to 1.44. That is too few expected variants to judge how well the gene tolerates losing a copy. Missense variants: 48 observed, 60.54 expected, observed/expected ratio (o/e) 0.79, 90% interval 0.63 to 1.01. Synonymous variants: 16 observed, 21.35 expected, observed/expected ratio (o/e) 0.75, 90% interval 0.51 to 1.14.
Homologues: Orthologues: chimpanzee RPL39L (98% identical). Paralogues in human: RPL39 (92% identical).
Diseases named in the same sentence as RPL39L in open-access papers:
RPL39L is named in the same sentence as 10 diseases in open-access papers, as found by Europe PMC text mining. Sharing a sentence is not in itself a finding about the gene and the disease. The quoted sentences say what the papers report.
breast carcinoma (3 papers, 2016 to 2025). "In human breast cancer tissue samples with heterogeneous cell type composition, RPL39L was also detectable, at lower abundance compared to pluripotent stem cells." (PMID 39041433, 2024). "However, the RPL39L mRNA was also observed outside of the germ cell lineage, particularly in ovarian and breast cancer tissues, as well as in lung cancer and neuroblastoma cell lines, where the expression appears to be driven by gene amplifications and CpG island hypomethylation." (PMID 39041433, 2024). "Cross-correlation analysis of SSR1/RPL39L was found only in colon and lung cancers, and the cross-correlation of PPARGC1B/CDKN2A was found only in colon and breast cancers, R-values of breast, colon and lung data." (PMID 39940786, 2025). "A classifier combining the expression signature of RPL39L, RPL26L1, and RPL21 has an even greater predictive power, comparable to that of genes that are most predictive for the relapse-free survival of breast cancer patients." (PMID 27884178, 2016). "However, there was no cross-correlation between SSR1/RPL39L in breast cancer, although a cross-correlation between SSR1/VARS, VARS/PPARGC1B, and PPARGC1B/RPL39L was found." (PMID 39940786, 2025).
lung carcinoma (2 papers, 2016 to 2025). "RPL39L is also consistently up-regulated in several cell-line models of breast and lung carcinoma, indicating that these cell lines could be used to study the function of this protein in tumorigenesis." (PMID 27884178, 2016).
colon cancer (1 paper, 2025). "In colon cancer, most likely because of the lack of data, cross-correlation identified only three correlating groups (EIF4E3/MEX3A, SSR1/RPL39L, and PPARGC1B/CDKN2A)." (PMID 39940786, 2025).
glioblastoma (1 paper, 2022). The most malignant astrocytic tumor (WHO grade IV). "Eight genes associated with glioblastoma prognosis were identified based on LASSO analysis: RPS10, RPS11, RPS19, RSL24D1, RPL39L, EIF3E, NUDT5, and RPF1." (PMID 36733371, 2022). "Two independent prognostic factors in glioblastoma, RPL39L and NUDT5, were identified." (PMID 36733371, 2022). "Eight genes—RPS10, RPS11, RPS19, RSL24D1, RPL39L, EIF3E, NUDT5, and RPF—were found to have an expression in the prognosis of glioblastoma." (PMID 36733371, 2022). "The expression of RPL39L and NUDT5 in glioblastoma cells and normal cells was detected using qRT-PCR." (PMID 36733371, 2022). "As can be seen in the figure, two genes, RPL39L and NUDT5, were significant in both univariate and multivariate Cox regression; therefore, these two genes can be considered independent prognostic factors of glioblastoma." (PMID 36733371, 2022). "Finally, univariate cox and multivariate cox analyses were performed, which identified RPL39L and NUDT5 as independent prognostic factors for glioblastoma." (PMID 36733371, 2022). "Both RPL39L and NUDT5 were highly expressed in glioblastoma cells." (PMID 36733371, 2022).
hepatocellular carcinoma (1 paper, 2016). A malignant tumor that arises from hepatocytes. "RPL39L, an RP gene paralog with testis-specific expression, which was previously found up-regulated in hepatocellular carcinoma and in some cancer cell lines, had the most striking bimodal pattern of expression across carcinoma types." (PMID 27884178, 2016).
lung adenocarcinoma (1 paper, 2025). A carcinoma that arises from the lung and is characterized by the presence of malignant glandular epithelial cells. "Hypo-methylation of cancer-specific CpG islands (CGIs) and RPL39L reactivation are important for the treatment and risk stratification of lung adenocarcinoma." (PMID 39940786, 2025).
ovarian carcinoma (1 paper, 2009). A malignant neoplasm originating from the surface ovarian epithelium. "We tested for the expression of five of the known retrogenes, UTP14C, PGK2, RPL10L, RPL39L and UBL4B in normal human ovary and ovarian cancers." (PMID 19333399, 2009).
cancer (6 papers, 2016 to 2025). A tumor composed of atypical neoplastic, often pleomorphic cells that invade other tissues. "RPL39L is a ribosomal protein paralog that is abundantly expressed in cancer cells and embryonic stem cells." (PMID 39940786, 2025). "Our data thus provide conclusive mass spectrometric evidence of RPL39L protein expression not only in male germ cells, but also in pluripotent cells and cancer cell lines." (PMID 39041433, 2024). "The RPL39L-to-core RP ratio also varied more than 30-fold across cancer types, in many cancers reaching the values observed in embryonic cells." (PMID 39041433, 2024). "With a novel mass spectrometric approach we revealed the expression of RPL39L protein beyond mouse germ cells, in human pluripotent cells, cancer cell lines and tissue samples." (PMID 39041433, 2024). "RPL39L was reported as a ribosomal protein with upregulated expression in cancers and played a role in drug resistance." (PMID 31729991, 2019). "Surprisingly, we found that RPL39L, an RP gene paralog exhibiting testis-specific expression, is consistently up-regulated in several carcinomas." (PMID 27884178, 2016). "Guimaraes and Zavolan analyzed The Cancer Genome Atlas (TCGA) data and found that certain ribosome protein (RP) genes, such as RPL39L, are commonly dysregulated in different cancer types; however, whether cancer cells and normal cells exhibit distinct ribosome heterogeneity remains unclear." (PMID 39086661, 2024). "The relatively high expression of RPL39L mRNA in extravillous trophoblast, breast glandular and pancreatic endocrine cells from the Human Protein Atlas, as well as multiple cancer types, suggested that RPL39L may support protein synthesis in the context of secretory processes." (PMID 39041433, 2024). "The RPL39L mRNA is also expressed outside of the male germ line, in normal and cancer cells, where its role is still unknown." (PMID 39041433, 2024).
RPL39L also shares sentences with these, for which no sentence is quoted: tumor (4 papers); viral infections (1).